CXCR2 (C-X-C motif chemokine receptor 2)
Diseases named in the same sentence as CXCR2 in open-access papers (continued):
Sharing a sentence is not in itself a finding about the gene and the disease.
leukemia (9 papers, 2017 to 2025). A malignant (clonal) hematologic disorder, involving hematopoietic stem cells and characterized by the presence of primitive or atypical myeloid or lymphoid cells in the bone marrow and the blood. "The IL-8/CXCR2 pathway expressed in leukemia-stromal cells is considered to be a potential prognostic factor and therapeutic target for leukemia and MDS26." (PMID 28266575, 2017). "Specifically, TNF-α mediates increased CXCL1 expression in CML BMSCs through signal transduction pathways, interacting with highly expressed CXCR2 in LSCs, thereby inducing a CXCR2 selection-dependent mechanism leading to the unlimited expansion of LSCs and leukemia progenitor cells." (PMID 40427609, 2025). "Furthermore, HSC-prog cells showed more interactions with other cells through known ligand–receptor pairs, such as leukaemia-associated ligands CXCL2, CXCL3, and FLT3, signalling to the receptors CXCR1 and CXCR2 expressed by CD14-mono and NK cells." (PMID 37615858, 2024). "Additionally, CXCR2 inhibition decreased LSCs viability in vitro and enhanced leukemia mice survival in vivo." (PMID 32443460, 2020). "Combining CXCR2 antagonist with TKIs effectively inhibits LSC proliferation in CML, significantly enhancing the inhibitory effect on leukemia cells and LSCs while promoting CML cell apoptosis." (PMID 40427609, 2025). "Additionally, abnormally activated CXCR2 expression induces dipeptidyl peptidase IV (DPP4/CD26), a marker of CML leukemia stem cells, and inhibits the PI3K/Akt/mTOR pathway cascade." (PMID 40427609, 2025). "Previously, we found that TKI-treatment could activate a non-canonical NFKB2/Cytokines/Chemokines/CXCR2 pro-leukemia inflammatory pathway to initiate the survival and relapse of FLT3-mut AML blasts ex vivo." (PMID 38023123, 2023). "As-A is shown herein to bind to HDC and exhibit a similar effect on leukemia development resulting in inhibition of several anti-inflammatory genes including TNF, IL1A/B, TNFA1P3, and CXCR2, but not IL6." (PMID 39769192, 2024).
osteoarthritis (9 papers, 2008 to 2025). A noninflammatory degenerative joint disease occurring chiefly in older persons, characterized by degeneration of the articular cartilage, hypertrophy of bone at the margins and changes in the synovial membrane. "Conversely, C-X-C motif chemokine receptor 2 (CXCR2) deficiency exacerbates osteoarthritis pathology by reducing ECM production (e.g., aggrecan, type II collagen) and increasing chondrocyte apoptosis via attenuated AKT signaling." (PMID 40860192, 2025). "CXCL1 promotes the expression of IL6 in synovial fibroblasts of osteoarthritis and RA patients via the CXCR2, c-Raf, MAPK, and AP-1 pathways." (PMID 35707715, 2022). "CXCR1/CXCR2 play a significant role in regulating tissue inflammation in a mouse model of osteoarthritis." (PMID 31139654, 2019). "Thus, inhibition of CXCR2 expression helps to control tissue inflammation, reduces tissue neutrophil infiltration, and alleviates clinical symptoms in Brucella osteoarthritis." (PMID 39967734, 2025). "Furthermore, although CXCR1 and CXCR2 are members of a family of chemokine receptors, they seem to play opposite roles in osteoarthritis." (PMID 34488536, 2021). "If CXCR1/2 signalling supports SOX9 expression, why did we not observe spontaneous osteoarthritis in CXCR2-deficient mice?" (PMID 25135253, 2015).
prostate tumors (9 papers, 2015 to 2025). "While most studies focused on the neutrophil/polymorphonuclear-MDSC recruitment via CXCR2, CXCL5-CXCR2 axis blocking resulted in a dramatic reduction of monocytic myeloid cells in prostate tumors." (PMID 34572939, 2021). "Pharmacological inhibition of CXCR2 was able to drive macrophages towards a pro-inflammatory state that induced growth arrest and senescence, specifically in prostate tumours deprived of PTEN expression." (PMID 34128831, 2021). "We analyzed RNA-sequencing (RNA-Seq) data (GSE114326) expression in a set of prostatic tumor samples collected from CXCR2+ NE cells compared to CXCR2− luminal cells." (PMID 34799554, 2021). "In PtenPC−/−, Myc-CaP and TRAMP-C1 allograft mouse models of PCa, MDSCs have been shown to be enriched in prostate tumours following surgical castration in a CXCR2-dependent manner." (PMID 34128831, 2021). "Our in vivo experimentation in three distinct prostate tumour models provides further compelling evidence for the contribution of CXCR1/CXCR2 signalling in adversely affecting RT outcome." (PMID 32743555, 2020). "Interestingly, TAMs expressing CXCR2 can infiltrate PTEN-null prostate tumors; CXCL2 activation of CXCR2 can direct macrophages towards an anti-inflammatory phenotype." (PMID 35053602, 2022). "The baseline and radiation-enhanced secretion of CXCL8 (and its orthologues CXCL1, CXCL2 and CXCL5) from PTEN-deficient prostate tumour epithelial cells exerts both autocrine and paracrine actions within the tumour microenvironment given the expression of CXCR1 and CXCR2 upon multiple cell types." (PMID 32743555, 2020). "In this study, we investigated the role of CXCR1 expression in prostate tumor, using the androgen-dependent cell line MDA-PCa-2b to stably express CXCR1 (MDA-PCa-2b-CXCR1) and, for control, cells expressing CXCR2 (MDA-PCa-2b-CXCR2) or vector alone (MDA-PCa-2b-vec)." (PMID 39766038, 2024). "CXCR1 expression, not CXCR2, upregulates the tumor suppressor ITM2A to inhibit prostate tumor growth." (PMID 39766038, 2024).
Alzheimer disease (8 papers, 2012 to 2025). A progressive, neurodegenerative disease characterized by loss of function and death of nerve cells in several areas of the brain leading to loss of cognitive function such as memory and language. "The chemokine interleukin-8 (IL-8) and its receptor CXCR2 contribute to chemotactic responses in Alzheimer’s disease (AD); however, properties of the ligand and receptor have not been characterized in animal models of disease." (PMID 26255110, 2015). "Nevertheless, their physiologic role could degenerate into neurotoxic effects during chronic neuroinflammation, as demonstrated in a murine model of Alzheimer’s disease for CCL2/CCR2 and CXCL1/CXCR2." (PMID 40801605, 2025).
cystic fibrosis (8 papers, 2011 to 2025). Autosomal recessive disorder caused by pathogenic variants in the CFTR gene (cystic fibrosis transmembrane conductance regulator), which encodes a chloride and bicarbonate channel expressed in epithelial cells, and follow the diagnosis criteria. "The role for IL-8 in CXCR1/CXCR2-mediated neutrophil recruitment in chronic airway inflammatory diseases, including COPD and cystic fibrosis, has been delineated." (PMID 22936990, 2012). "NET formation in CF is dependent on CXCR2-mediated signals and pharmacological inhibition of NET formation ameliorates lung inflammation in a mouse model of cystic fibrosis." (PMID 21779371, 2011).
depression (8 papers, 2022 to 2025). "We demonstrated that high IL-8 levels in the tumor microenvironment of depressed patients activated CXCR2, mediating the cancer-promoting effects of depression." (PMID 40839237, 2025). "In this study, we revealed that CXCR2 is a key target that mediates the procancer effect of depression and that senkyunolide H can reverse the probreast cancer effect of depression by regulating the inhibition of CXCR2 activation." (PMID 40839237, 2025). "We used in vivo experiments to verify the effect of CXCR2 on the cancer-promoting effects of depression." (PMID 40839237, 2025). "Recently, inhibition of CXCR2 prevented chronic stress-induced depression-like behaviors in mice, suggesting CXCR2 as a potential novel therapeutic target for patients with depression." (PMID 40473930, 2025). "Activation of the G-protein coupled receptor CXCR2 by the chemokine CCLX1 has been suggested to induce depression-like symptoms." (PMID 40473930, 2025). "Collectively, these findings underscore the pivotal role of CD8+ TSCM cells in depression pathophysiology and highlight the potential of CXCR2 inhibitor as a therapeutic strategy to modulate gut microbiota metabolism and neuroinflammation in MDD." (PMID 41258106, 2025). "For instance, Hyperoside significantly mitigates depression-like behaviors in chronic stress-induced mice by inhibiting the NLRP1 inflammasome and modulating the CXCL1/CXCR2/BDNF signaling pathway, leading to improved anhedonia and reduced immobility time." (PMID 40444002, 2025). "To research the influence of Hyp on the depression-like behavior of mice mediated by the NLRP1 inflammasome, we detected the mRNA levels of CXCL1, CXCR2, and BDNF in the hippocampus of mice." (PMID 36556951, 2022). "C-X-C motif chemokine receptor 2 (CXCR2) is the receptor of chemokine CXCL1, and the inhibitor of CXCR2 (SB265610) prevented chronic stress-induced depression-like behaviors in mice." (PMID 36408212, 2022).
ulcerative colitis (8 papers, 2015 to 2025). An inflammatory bowel disease involving the mucosal surface of the large intestine and rectum. "In ulcerative colitis (UC), increased epithelial CXCR1 protein expression was found and a meta-analysis afterwards identified CXCR1 and CXCR2 as additional UC risk loci." (PMID 26230114, 2015). "Additionally, in ulcerative colitis, CXCR2 signaling facilitates neutrophil migration to the gut mucosa, aggravating intestinal inflammation and ulceration." (PMID 39062109, 2024). "Numerous studies showed that the expression of CXCR1 and/or CXCR2 increased in many inflammatory disease, such as ulcerative colitis and hyperoxia-induced lung injury, so that massive neutrophils could be recruited into the site of inflammation." (PMID 31988368, 2020). "CXCR2 and S100A9 are neutrophil-related biomarkers and potential therapeutic targets in ulcerative colitis." (PMID 38034382, 2023).
cervical cancer (7 papers, 2017 to 2025). A primary or metastatic malignant neoplasm involving the cervix. "In conclusion, the combined inhibition of IDO-1 and CXCR-2 is helpful in the antitumor response against preclinical cervical cancer." (PMID 37626777, 2023). "Our results revealed that the simultaneous inhibition of IDO-1 and CXCR-2 induced antitumor effects in cervical cancer." (PMID 37626777, 2023). "By binding to the endothelial receptor CXCR2, these chemokines are involved in endothelial tube formation as well as in the proliferation of cervical cancer cells and in the clone-formation that is induced by the overexpression of AKIP1." (PMID 34833360, 2021). "In cervical cancer, CXCL1 promotes tumor cell migration and invasion through its receptor CXCR2 while modulating the immune microenvironment to suppress anti-tumor immune responses." (PMID 40517358, 2025). "In this study, the K14E7E2 mouse was used as a cervical cancer model to evaluate the inhibition of indolamine-2,3-dioxygenase 1 (IDO-1) and C-X-C chemokine receptor type 2 (CXCR-2) as potential anti-tumor targets." (PMID 37626777, 2023). "Upregulated CXCL5 in patients with cervical cancer increases the oncogenic potential of HeLa cervical cancer cells by increasing the phosphorylation of ERK1/2 and Akt and the gene expression of CXCR2." (PMID 37373052, 2023). "CXCL5 and its receptor CXCR2 are expressed by HeLa cells and CXCL5 is upregulated in cervical cancer tissues." (PMID 34833360, 2021).
esophageal squamous cell carcinoma (7 papers, 2015 to 2025). Esophageal squamous cell carcinoma (ESCC) is a type of esophageal carcinoma (EC) that can affect any part of the esophagus, but is usually located in the upper or middle third. "LAMC1 promoted CXCL1 secretion, which stimulated inflammatory CAF formation via CXCR2-pSTAT3, which in turn accelerates esophageal squamous cell carcinoma progression." (PMID 36246404, 2022). "In this study, we demonstrate the significance of CXCR2 expression and validate the effects of CXCR2 expression and postoperative complications on long-term prognosis of esophageal squamous cell carcinoma using resected specimens." (PMID 26231560, 2015). "Previously, we reported that the expression of both IL-8 and CXCR2 in esophageal squamous cell carcinoma (ESCC) was an independent predictor of prognosis." (PMID 26231560, 2015). "LAMC1 secretion was associated with the formation of inflammatory CAFs in esophageal squamous cell carcinoma, and upregulation of LAMC1 expression promoted CXCL1 secretion, which stimulated inflammatory CAFs via CXCR2-pSTAT3 and thus promoted tumor progression." (PMID 37588985, 2023).
fibrosis (7 papers, 2020 to 2026). the formation of excess fibrous connective tissue in an organ or tissue in a reparative or reactive process. "A fibrosis-related Cxcr2+ EC subset is identified, and its specific depletion effectively mitigates renal fibrosis." (PMID 41887221, 2026). "In this sense, the reduced fibrosis induced by Ladarixin treatment, in both chronic asthma and Bleomycin-induced fibrosis model, may be, also, due to the blockage of CXCR2 on fibroblasts." (PMID 33123138, 2020).
liver fibrosis (7 papers, 2013 to 2024). "To further investigate the role of CXCL2 in liver fibrosis, we examined the therapeutic potential of a CXCR2 inhibitor in a mouse liver fibrosis model." (PMID 34830293, 2021). "While the induction of the receptors CD74 and CXCR4 is comparable between the models, there is a marked up-regulation of chemokine receptor CXCR2 in MCD-treated mice compared to the CCl4-induced liver fibrosis model." (PMID 33525493, 2021). "CXCL-1 is a potent agonist for CXCR2 which recruits neutrophils to the site of inflammation or injury during liver disease, and plasma levels of CXCL1 are associated with liver fibrosis in HCV-infected patients." (PMID 27590274, 2016). "Immunostaining of HIV/HCV liver biopsies from co-infected patients reveals that the progression of liver fibrosis correlates with a reduced expression of CXCR2." (PMID 24736615, 2014). "Since profibrogenic functions of HSCs are induced through CXCR2 and the CXCR2 ligand CXCL8 is associated with hepatic macrophage accumulation in human liver fibrosis, CXCR2 evolved as an attractive target for liver fibrosis treatment." (PMID 24646914, 2014). "Moreover, targeting CXCL2 by CXCR2 inhibitors attenuated the activation of HSCs and reduced liver fibrosis." (PMID 34830293, 2021). "The study demonstrated that PPARα activation attenuated liver fibrosis by reducing the expression of pro-inflammatory cytokines and chemokines, including CXCR1 and CXCR2, thus highlighting the potential link between PPARα and CXCR1/2 in liver inflammation and fibrosis." (PMID 39627194, 2024). "By administering CXCR2 inhibitor (SB225002) or Oil preventively to CCl4-treated mice, we found that SB225002 significantly weakened liver injury and attenuated CCl4-induced liver fibrosis by H&E staining and Sirius Red staining." (PMID 34830293, 2021). "Thus, CCR5, CXCR2, CXCR4 and CXCR6 antagonists or the application of CXCL9 may serve for prevention and treatment of liver fibrosis." (PMID 24646914, 2014).
mastitis (7 papers, 2016 to 2024). Inflammation of breast tissue during lactation or postpartum due to an obstructed duct or infection. "In sheep, CXCR2 has been implicated in clinical mastitis and resistance to gastrointestinal nematode infection." (PMID 39080565, 2024). "It has been documented that the mutation at point +735 G>C could change the amino acid glutamine to histidine in the amino chain of CXCR2, which is linked to calcium signaling and G-protein interaction and has a key role in mastitis." (PMID 36911690, 2023). "CXCR2 may well be associated with the immune response during mastitis however, the direction of regulation depends on the type of infection, since it is a target gene of miR-145, which was found to be down-regulated in both comparisons." (PMID 33676576, 2021). "Additionally, previous literature documents that the CXCR2 gene polymorphism is closely interrelated with bovine mastitis susceptibility or resistance." (PMID 31417691, 2019). "However, whether CXCR2 gene polymorphism is related with clinical mastitis in sheep still needs to be further investigated and explored." (PMID 31417691, 2019). "We have analysed the missense SNPs belonging to six genes (CXCR2, CXCL8, TLR4, BRCA1, LTF, BOLA-DRB3) and identified one marker (rs110124025) in BOLA-DRB3 that was associated with frequency of mastitis and with the number of affected quarters." (PMID 37174521, 2023). "The objective of our study was to analyse 89 missense SNPs belonging to six genes (CXCR2, CXCL8, TLR4, BRCA1, LTF, BOLA-DRB3), which were found to be associated with genetic resistance or susceptibility to mastitis." (PMID 37174521, 2023).
metastatic melanoma (7 papers, 2019 to 2025). A melanoma that has spread from its primary site to another anatomic site. "In addition to these promising pre-clinical studies, CXCR2-transduced autologous tumor-infiltrating lymphocytes are under clinical investigation in patients with metastatic melanoma." (PMID 34944914, 2021). "CXCR2 antagonists are also being evaluated in combination with immune checkpoint inhibitor pembrolizumab in advanced solid tumors (NCT03473925) and in metastatic melanoma (NCT03161431, not yet recruiting) (ClinicalTrials.org)." (PMID 30873179, 2019).
nasopharyngeal carcinoma (7 papers, 2017 to 2025). A carcinoma arising from the nasopharyngeal epithelium. "In this study, we aimed to confirm the expression of CXCR2 in human nasopharyngeal carcinoma and attempted to study the antitumor and radiosensitization effects and mechanisms of SB225002 in NPC." (PMID 34124076, 2021). "We then confirmed the expression of CXCR2 in nasopharyngeal carcinoma cell lines by flow cytometry (FCM) and Western blot." (PMID 34124076, 2021). "Additionally, CXCR-2 inhibition in the nasopharyngeal cancer cell line, suppression of proliferation, and induction of apoptosis were observed when inhibiting the MAPK pathway." (PMID 37626777, 2023). "CXCR2, a member of the G-protein-coupled cell surface chemokine receptor family, is commonly found on leukocytes, endothelial cells and tumor cells including nasopharyngeal carcinoma cells." (PMID 34124076, 2021). "To explore the effect of CXCL8-CXCR2 signaling in nasopharyngeal carcinoma, we performed immunohistochemistry staining for CXCR2 and CXCL8 in an NPC tissue microarray and found CXCR2 localized in both tumor cells and stromal cells; CXCL8 was frequently observed in the cytosol of tumor cells." (PMID 34124076, 2021). "Furthermore, we identified that treatment with CXCR2 antagonist SB225002 of nasopharyngeal carcinoma cell lines resulted tumorigenesis inhibition in vitro and in vivo." (PMID 34124076, 2021). "In nasopharyngeal carcinoma, CXCL5/CXCR2 axis promoted cell migration and invasion by inducing EMT through ERK/GSK-3β/Snail signalling pathway." (PMID 36151545, 2022). "However, how the activity of CXCR2 and its ligand CXCL8 affects the development of nasopharyngeal carcinoma (NPC) remains unknown." (PMID 34124076, 2021). "In nasopharyngeal carcinoma (NPC) cell lines, C666-1, MIF/IL-8/ CXCR2 signaling could enhance the growth of the tumor spheres." (PMID 27788497, 2017).